ACSL4 (acyl-CoA synthetase long chain family member 4)
Diseases named in the same sentence as ACSL4 in open-access papers (continued):
Sharing a sentence is not in itself a finding about the gene and the disease.
cancer (continued). "Once detached from ECM, α6β4 integrin on cancer cells inhibited the expression of long polyunsaturated fatty acid-rich enzyme acyl-CoA synthetase long-chain family member 4 (ACSL4) (essential for ferroptosis) through Src and signal transducer and activator of transcription 3 (STAT3) pathways." (PMID 37369681, 2023). "Therefore, understanding the ACSL4-mediated switch between pro-death and anti-death mechanisms will be a crucial step towards developing more effective cancer therapies." (PMID 37372148, 2023). "Targeting ACSL4 in cancer treatment, whether it involves forced expression or inhibition, will most likely not comprise a lone therapy but will more likely function as part of a combined therapy." (PMID 37306503, 2023). "G9P infection was found to downregulate the expression of ACSL4 (acyl-CoA synthetase long chain family member 4), a gene involved in inflammation, cell death, female fertility, and cancer regulation, and FASN (fatty acid synthase regulating virus entry, host IFN response) (data not shown)." (PMID 37515094, 2023). "Indeed, biochemical evidence correlates ferroptosis with cancer radiotherapy, which results in ACSL4 expression triggering PUFA peroxidation and ferroptosis in different tumors, including melanoma and esophageal cancer." (PMID 38139106, 2023). "However, ACSL4-dependent ferroptosis can also play a protective role in certain contexts for cancer cells." (PMID 37372148, 2023). "On the other hand, in some instances, such as cancer, activation of ferroptosis might comprise a viable treatment option, in which case expression of ACSL4 would be a requirement for sensitivity to ferroptosis-inducing reagents." (PMID 37306503, 2023). "Induction of ACSL4-dependent ferroptosis is a promising therapeutic option for several cancers." (PMID 37372148, 2023). "As ACSL4 is an essential enzyme that incorporates PUFAs, such as AA, into phospholipids, a critical step to ferroptosis, the authors showed that RB loss increased lipid peroxidation and ferroptotic potential of cancer cells, which was abolished upon concurrent ACSL4 inhibition." (PMID 37183818, 2023). "Therefore, IFN-γ combined with AA is thought as the endogenous triggering factor for ACSL4-mediated cancer cell ferroptosis, and immune checkpoint inhibitors (ICIs) can significantly enhance the anti-tumor effect." (PMID 38288118, 2023). "A recent meta-analysis of public databases comparing ACSL4 mRNA and protein expression in a variety of cancers confirmed that ACSL4 expression is decreased in malignant versus normal breast tissue, while being differentially expressed as a function of molecular subtype." (PMID 37306503, 2023). "Yet, regardless of whether ACSL4 mRNA expression is generally increased or decreased in malignant versus normal cells, ACSL4 expression is positively correlated with a more aggressive phenotype of that particular cancer." (PMID 37306503, 2023). "Interestingly, recent studies have shown that the accumulation of lipid peroxides induces the activation of PKCβII in cancer cells, and PKCβII can also interact with the Thr328 site of ACSL4 to activate ACSL4." (PMID 38288118, 2023). "Therefore, cancers can be of two types according to the role of ACSL4 in promoting lipid metabolism and ferroptosis." (PMID 37064872, 2023). "In general, low ACSL4 expression has shown a beneficial role in pan-cancer." (PMID 35126480, 2022). "Although ACSL4 is the activator of ferroptosis in distinct cancers, whether ferroptosis/ACSL4 benefit to improve the outcome of tumors need careful identification." (PMID 35910359, 2022). "Therefore, further in vivo and in vitro experiments are needed to realize the mechanisms of ACSL4 in different cancer types at the cellular and molecular level." (PMID 35126480, 2022).
cancer (continued). "High-fat intervention on cancer cells could inhibit erastin-induced ferroptosis by decreasing the expression of ACSL4." (PMID 35910359, 2022). "Glycosylation was a common PTM in cancer and immunoprecipitation test demonstrated that ACSL4 protein could be O-GlcNAcylated to maintain protein stability and continuously promote cancer cell proliferation." (PMID 35910359, 2022). "The results showed that ACSL4 expression was significantly associated with NK, B cells, macrophages, DC, CD4+ T cells, CD8+ T cells, monocytes and neutrophil infiltration in 13, 16, 19, 24, 25, 26, 28 and 31 cancer types." (PMID 35126480, 2022). "ACSL4 is negatively correlated with DNA methylation levels in most cancers." (PMID 35126480, 2022). "Since the intrinsic modulators that contribute to ALOX12 activation remain largely unknown, a designed ALOX12 activator becomes indispensable and hence holds great promise to promote ACSL4-independent ferroptosis of cancer cells." (PMID 36517470, 2022). "These analyses revealed that while treatment with arachidonic acid (AA, a 20-carbon chain PUFA with four double bonds; C20:4) alone triggers little ferroptosis, AA synergizes with IFNγ to induce potent ferroptosis in diverse cancer cell lines in an ACSL4-dependent manner." (PMID 35459217, 2022). "Exogenous oxygen radicals generated by photodynamic therapy could peroxidize PUFAs (accompanied with higher expression of ACSL4) and promote ferroptosis to cancer treatment." (PMID 35910359, 2022). "we found that ACSL4 expression was negatively correlated with methylation levels in 19 cancers." (PMID 35126480, 2022). "In summary, the combined analysis of the three databases shows that ACSL4 has prognostic value in certain cancers, which may be beneficial or harmful." (PMID 35126480, 2022). "Subsequently, ACSL4 methylation in different cancers was analyzed using the UALCAN database." (PMID 35126480, 2022). "Enhanced expression of particular ACSL4 was confirmed to be a feature of some more aggressive cancers and may contribute to the oncogenic phenotype." (PMID 35910359, 2022). "In this study, it was found that cancers with high ACSL4 expression (LICH, COAD, STAD) had high levels of MDSC infiltration, while cancers with low ACSL4 expression (BRCA, KIRC, LUSC, SKCM) had high levels of MDSC infiltration, and had poor prognosis and survival in BRCA and SKCM." (PMID 35126480, 2022). "ACSL4 could activate fatty acids by adding CoA and abnormal expression of ACSL4 was reported in several cancers and may affect prostaglandin biosynthesis, fatty acid β-oxidation, ferroptosis, and phosphatidyl chain remodeling." (PMID 35910359, 2022). "Targeting the molecular mechanisms of ACSL3 and ACSL4 may provide more therapies for cancer treatments." (PMID 36497375, 2022). "In this study, we speculate that the mechanism of ACSL4 in cancer is closely related to the IGF signaling pathway." (PMID 35126480, 2022). "Therefore, our study identifies TPCI as the first ALOX12 activator to induce ferroptosis independent of ACSL4, which renders a viable therapeutic approach on the basis of distinct ferroptosis of cancer cells, regardless their ACSL4 expressions." (PMID 36517470, 2022). "Although multiple genes, such as ACSL4, PTGS2, NOX1, GPX4, FTH1, and SLC7A11, have been shown to be associated with ferroptosis, it is unclear how ferroptosis is genetically programmed in cancers." (PMID 35321435, 2022). "There are few studies on the relationship between ACSL4 gene alteration and cancer." (PMID 35126480, 2022). "However, a large variety of cancer cells have insufficient or downregulated expression of ACSL4, so that they are resistant to GPX4-mediated ferroptosis." (PMID 36517470, 2022).
cancer (continued). "Researchers have found that ACSL4 could be considered a new therapeutic target to regulate the expression of transporters involved in anti-cancer drug resistance through the mTOR pathway." (PMID 36497375, 2022). "ACSL4 activates PUFAs and sensitizes cancer cells to ferroptosis in immunotherapy-related settings." (PMID 35910359, 2022). "This has been attributed to the ability of these cancer cells to increase the synthesis and uptake of polyunsaturated fatty acids (PUFAs) and their resultant transformation into cytotoxic lipid peroxides (and lipid radicals) by the ACSL4/LPCAT3/ALOX pathway." (PMID 34429409, 2021). "The significantly high levels of ACSL4 detected in these exosomes may serve as the protective signal that promotes the survival of neighboring cancer cells." (PMID 33466836, 2021). "The ACSL4 protein plays a role in the survival of cancer cells." (PMID 33466836, 2021). "A previous study revealed that activation of SRC can protect cancer cells from ferroptosis by suppressing the expression of ACSL4, an enzyme that enriches membranes with PUFAs and is required for ferroptosis, revealing the inhibitory role of SRC in ferroptosis." (PMID 34764976, 2021). "The α6β4 integrin mediates activation of Src and STAT3 to suppress expression of ACSL4, an enzyme that enriches membranes with long polyunsaturated fatty acids and is required for ferroptosis to protect adherent epithelial and carcinoma cells from ferroptosis induced by erastin." (PMID 34717678, 2021). "In addition to regulating the synthesis and degradation of lipids, ACSL4 has been found overexpressed in several origins of cancer." (PMID 32751249, 2020). "Given the emerging importance of ACSL3 and ACSL4 in cancer, we describe here a series of subcellular fractionation experiments aimed at elucidating and comparing the subcellular distributions of these enzymes in cancer cells." (PMID 29450800, 2018). "The detailed mechanism by which ACSL4 modulates cancer progression need to be further investigated." (PMID 27171439, 2016). "Thus, the inhibition of ACSL1/ACSL4/SCD axis by means of the selective effect of these drugs on cancer cells arises as a promising therapeutic strategy." (PMID 26451612, 2015). "Therefore, it is important to determine the role and molecular mechanism that govern the relationship between ACSL4 expression and the metabolic pathway of AA in cancer cells." (PMID 21085606, 2010). "ACSL4 deletion or treatment with liproxstatin-1, an inhibitor of ferroptosis, significantly reduced 4-hydroxynonenal (4-HNE) levels, while the level of 4-HNE in esophageal cancer tissues after radiotherapy was significantly associated with better clinical prognosis of cancer patients." (PMID 41293165, 2025). "Furthermore, a previous study suggested that the proto-oncogenic transcriptional co-activator YAP might promote ferroptosis by regulating ACSL4, in turn involving in the cancer progression." (PMID 38564125, 2025). "As the TGF-β signaling pathway is known to regulate various cellular processes in cancer, including cell growth, cell differentiation, and apoptosis, we thus hypothesized that ACSL4 contributed to OS cell progression by regulating TGF‐β/Smad2 signaling pathway." (PMID 38564125, 2025). "Furthermore, the elevated expression of ACSL4 observed in certain cancer tissues suggests that it could serve as a potential molecular target for triggering ferroptosis." (PMID 40932861, 2025). "Next, we examined the expression of acyl-CoA synthetase long-chain family member 4 (ACSL4), arachidonate 5-lipoxygenase (ALOX5), and arachidonate 15-lipoxygenase (ALOX15), which are implicated in lipid peroxidation, a major cause of ferroptosis in carcinoma cells." (PMID 41339896, 2025). "Therefore, further therapies aimed at increasing ferroptosis sensitivity could consider the cancer-promoting function of ACSL4." (PMID 38993573, 2024).
cancer (continued). "Therefore, by increasing ACSL4 expression and the rate of lipid peroxidation, RB1 loss raises the extent that cancer cells depend on GPX4 to block ferroptosis and, on the other hand, sensitizes cancer cells to GPX4 inhibitors or, in general, ferroptosis inducers." (PMID 37183818, 2023). "Inhibitors of ACSL4 activity could prove useful in slowing proliferation of ACSL4-positive cancers." (PMID 37306503, 2023). "Therefore, targeting ACSL4 could be a potential strategy for treating metabolic diseases and cancer." (PMID 37372148, 2023). "However, on the other hand, ACSL4 is a potential anti-cancer target." (PMID 37372148, 2023). "In addition, ACSL4 is positively correlated with immune infiltration in cancers." (PMID 35126480, 2022). "Similarly, we assessed the effect of ACSL4 CNV on prognosis in patients with various cancers." (PMID 35126480, 2022). "Notably, ACSL4 mRNA expression was low in both cancers and the prognosis was poor." (PMID 35126480, 2022). "Moreover, miR-454-3p/ ACSL4 axis may be just one of the downstream mechanisms of ZONs-induced anti-RCC cancer effect and other potential targets of ZONs should be explored by more studies." (PMID 35368896, 2022). "Moreover, ACSL4-mediated lipid metabolism has been shown to promote cancer metastasis." (PMID 35372083, 2022). "Thus, it could be speculated that ACSL4 may represent a double-edged sword target, since both enhances cell proliferation and invasion and sensitizes cancer cells to ferroptotic stimuli." (PMID 31344914, 2019). "Furthermore, enhanced expression of particular ACSL isoforms, such as ACSL4, is a feature of some more aggressive cancers and may contribute to the oncogenic phenotype." (PMID 29450800, 2018). "Taken together, LA-m-mediated sensitization of cancer cells to ferroptosis was attributed to its ability to upregulate CD36 and ACSL4." (PMID 40077664, 2025). "For example, MYC enhances cellular antioxidant capacity and suppresses ferroptosis in cancer stem cells by activating CPT1A expression, which in turn activates the NRF2/GPX4 system and reduces phospholipid polyunsaturated fatty acids via ACSL4 downregulation." (PMID 40732268, 2025). "Radiation upregulates ACSL4, represses GPX4 expression, and promotes ferroptosis in several cancer cell lines." (PMID 39425547, 2025). "Macrophages can undergo polarization from the M2 to M1 phenotype through ACSL4-induced ferroptosis and STING activation, suggesting that ACSL4 activation is a promising strategy for macrophage reprogramming in cancer therapy (Cao 2024;, Chen 2023)." (PMID 40285867, 2025). "PPAR signaling pathway has been previously reported to be regulated by NAT10 through ac4C modification of genes such as ELOVL6, ACSL1, ACSL3, ACSL4, ACADSB, and ACAT1, thus modulating fatty acid metabolism in cancer cells." (PMID 40123006, 2025). "Among these, PEBP1/STK11 co-expression strongly negatively correlates in all cancer types with enzymes that increase the biosynthesis of fatty acids such as members of the ACSL family (ACSL1, ACSL3, ACSL4, ACSL5, and ACSL6)." (PMID 40806276, 2025). "Along with ACSL4 and ACSL1, ACSL5 has also been considered an immune-dependent cancer suppressor gene." (PMID 41288931, 2025). "For example, ACSL4 is a positive regulator of ferroptosis, whereas ACSL3 contributes to the acquisition of ferroptosis resistance in cancer cells." (PMID 40102409, 2025). "Meanwhile, EXO@CAT NVs provided ACSL4, an important isozyme involved in the metabolism of PUFAs, contributing to an accumulation of LPO to render cancer cells more sensitive to ferroptosis." (PMID 39744220, 2025). "Ongoing preclinical studies are exploring additional small-molecule inhibitors of ACSL4, including rosiglitazone, a PPAR-γ agonist, which has been reported to inhibit ACSL4 in PPAR-γ, to unravel their therapeutic potential in cancer treatment." (PMID 38610991, 2024).
cancer (continued). "For example, upon uptake by cancer cells, CAF-secreted exosomal miR-3173-5p sponges ACSL4 and thereby suppresses ferroptosis, inducing acquired gemcitabine resistance in pancreatic cancer." (PMID 39614322, 2024). "Based on many present studies, the influence of ACSL4 and MYL6 on cell structure and movement is closely related to the occurrence and development of cancer, inflammation, ischemia–reperfusion, and other diseases." (PMID 39262873, 2024). "This is also reflected by the correlation (ELOVL5, FADS2 and ACSL4) and anti-correlation (FASN and SCD) of these enzymes with Zeb1 expression in cancer cell lines." (PMID 39009641, 2024). "In addition, ACSL4 could play a controversial role in cancer." (PMID 39335604, 2024). "ACSL4 was upregulated in EGFR-mutant lung ADC cell lines and the upregulation of ACSL4 led to a higher energy metabolism in EGFR-mutant cells, enabling cancer cells to enhance cell growth and acquire drug resistance." (PMID 38539505, 2024). "For example, reduced expression of sirtuin 3 (SIRT3) in patients with gallbladder cancer leads to the inhibition of ACSL4 through AKT serine/threonine kinase (AKT/PKB) signaling, in contrast to the normal tissues surrounding the cancer." (PMID 37372148, 2023). "Therefore, the combined use of IFN-γ and fatty acids may promote the rapid amplification of lipid peroxides through positive feedback between PKCβII and ACSL4, reaching a lethal level of cancer cell ferroptosis and enhancing the ability of IFN-γ to induce ferroptosis." (PMID 38288118, 2023). "Overall, our findings suggest that gastrodin acts as an anti-cancer agent by inducing ferroptosis and inhibiting cell proliferation in HOXD10/ACSL4-dependent pathways." (PMID 38138552, 2023). "Whereas Dt exerts a greater antiproliferation role on PC3 than on DU145 cells (this study), in agreement with a higher ACSL4 gene relative expression in PC3 than DU145 cells, both cancer cell lines display activation of a similar ferroptosis pathway." (PMID 36829917, 2023). "To evaluate the clinical relevance of CYP1B1 and ACSL4 in CRC tumors, we first compared the expression of CYP1B1 and ACSL4 in CRC cancer tissues and adjacent normal tissues." (PMID 37059712, 2023). "ACSL4 regulates the role of METTL5 in fatty acid metabolism and thus facilitates cancer progression." (PMID 37055798, 2023). "We further explored the effect of 5 hub genes (ACSL4, FANCD2, HIF3A, HSPA5, and PSMB7) in 33 kinds of cancer in the TCGA database." (PMID 35652069, 2022). "Meanwhile, GSCA database was used to analyze the SNV of ACSL4, and SNV was found in 19 kinds of cancer." (PMID 35126480, 2022). "While acyl-CoA synthetase long-chain family member 4 (ACSL4) and hypoxia-inducible factor-1/2 (HIF-1/2) play important roles in cancer development, they can also upregulate the ferroptosis sensitivity." (PMID 35372083, 2022). "Additional studies are needed to better understand ferroptosis and anti-cancer immunity and how to target ACSL3 or ACSL4 for better immunotherapeutic efficacy." (PMID 36497375, 2022). "ACSL4 is required for cellular uptake of exogenous PUFA and for cancer cells to exhibit a more malignant phenotype." (PMID 36497375, 2022). "In fact, upregulated ACSL4 upon YAP activation prompts ferroptosis and ACSL4-knockout cancer cells exhibit significantly decreased levels of AA-CoA and Ada-CoA, and in-turn, induction of ferroptosis by RSL3 is reduced." (PMID 35531466, 2022). "In order to determine the protein expression of ACSL4 in various cancers, the UALCAN database was used to analyze the ACSL4 protein expression." (PMID 35126480, 2022). "It is noted that the expression levels of ACSL4 varied significantly in these cells, and the TPCI-induced ferroptosis was applicable to all of these human cancer cell lines." (PMID 36517470, 2022).